ACLY (ATP citrate lyase)
Diseases named in the same sentence as ACLY in open-access papers (continued):
Sharing a sentence is not in itself a finding about the gene and the disease.
Sepsis (7 papers, 2021 to 2025). Sepsis is defined as life-threatening organ dysfunction caused by a dysregulated host response to infection. "Impaired glycolysis in Tgr5-deficient macrophages cumulates in reduced ATP citrate lyase (Acly) expression and histone acetylation, which is important for silencing proinflammatory genes and controlling hyperinflammation during L.m. sepsis." (PMID 41377671, 2025). "Collectively, these results revealed that ACLY levels were closely associated with the severity of patients with sepsis, implying the potentially detrimental effects of intrinsic ACLY on cellular functions." (PMID 37414769, 2023). "Serum ACLY level is an additional diagnostic and prognostic biomarker in pediatric patients with sepsis." (PMID 33378581, 2021). "In our present study, ACLY was almost undetectable in sera of healthy children, and serum ACLY level achieved a higher diagnostic value for pediatric sepsis." (PMID 33378581, 2021). "Serum ACLY level is an additional diagnostic and prognostic biomarker in pediatric patients with sepsis.The relationship between serum ACLY and IL‐18 and underlying mechanisms involved in pathophysiology of sepsis need further study in the future." (PMID 33378581, 2021). "In summary, we first identified serum ACLY as a new diagnostic and prognostic biomarker in pediatric patients with sepsis." (PMID 33378581, 2021). "Our findings revealed that ACLY promoted EC gluco-lipogenic metabolism and proinflammatory response through acetylation-mediated MYC transcription, suggesting ACLY as the potential therapeutic target for treating sepsis-associated EC dysfunction and organ injury." (PMID 37414769, 2023). "Taken together, these findings provide a framework to understand the role of ACLY in regulating the proinflammatory activation and gluco-lipogenesis in ECs, highlighting the potential of ACLY as a novel therapeutic target for treating sepsis-associated EC dysfunction and organ injuries." (PMID 37414769, 2023). "In this study, we for the first time demonstrated the regulatory mechanism of ACLY-mediated EC dysfunction in sepsis." (PMID 37414769, 2023). "In a pilot clinical study, an increased level of serum ACLY was identified in pediatic patients with sepsis." (PMID 37414769, 2023). "All these data pinpoint the involvement of ACLY in sepsis and open a new therapeutic avenue for treating inflammation-related diseases." (PMID 37414769, 2023). "Higher levels of ACLY were detected in sera of pediatric patients with sepsis than that of healthy children." (PMID 33378581, 2021). "Serum ACLY concentrations on PICU admission were significantly higher in patients who fulfilled sepsis criteria compared with healthy control, and the basic level of serum ACLY in healthy control was very low." (PMID 33378581, 2021). "We also investigated the ACLY/NF-κB axis in patients with sepsis in the early hyperinflammatory phase." (PMID 34831186, 2021). "Nevertheless, our findings strongly support future functional and clinical analyses on the role of ACLY in the pathophysiology of sepsis." (PMID 33378581, 2021). "ACLY levels ≤21 ng/ml on PICU admission predicted an unfavorable prognosis among patients with sepsis with a sensitivity of 87.5% and a specificity of 67.6%." (PMID 33378581, 2021). "We observed higher levels of ACLY proteins in patients with sepsis than in the age-matched healthy controls." (PMID 34831186, 2021). "All these data pinpoint the involvement of ATP citrate lyase in sepsis and open a new therapeutic avenue." (PMID 34502162, 2021). "Our previous study has shown that the inhibition of ATP citrate lyase (ACLY)-related gluco-lipogenesis could ameliorate sepsis-induced multiple organ dysfunction via inhibiting FoxO1-MYC-mediated vascular activation." (PMID 40369168, 2025).
Sepsis (continued). "Moreover, we found the protective effects of ACLY inhibitors on vital organ injuries in mice with sepsis, which is supported by recent studies that proposed ACLY inhibition as a potential treatment target for cancer, sepsis, and/or other metabolic diseases." (PMID 37414769, 2023). "Additionally, the level of fumarate, which has been reported to have beneficial effects in sepsis and chronic active multiple sclerosis lesions, was also significantly increased by ACLY inhibition." (PMID 37414769, 2023). "The results showed that serum ACLY levels could be an additional biomarker for sepsis occurrence with a high value of area under ROC curve (AUC) of 0.855 (95% CI: 0.757–0.952)." (PMID 33378581, 2021). "This study first demonstrated that serum ACLY level could be a candidate for the prognostic value of sepsis." (PMID 33378581, 2021). "Since NF-κB activation is increased in patients with sepsis, where the main heterodimer characterized is p50/p65, we examined whether ACLY-mediated NF-κB acetylation is a feature of this condition." (PMID 34831186, 2021). "Moreover, serum ACLY levels were correlated to platelet count, IL‐18 levels, and monocyte counts in pediatric patients with sepsis, implying the potential roles of ACLY in immunometabolic regulation in sepsis." (PMID 33378581, 2021). "Notably, sepsis in the early hyperinflammatory phase triggers ACLY-mediated NF-κB acetylation." (PMID 34831186, 2021). "Further studies are needed to understand the distinct roles of ACLY and ACSS2 in EC dysfunction during sepsis." (PMID 37414769, 2023). "However, the serum level of ACLY and its clinical relevance in sepsis is totally unknown." (PMID 33378581, 2021). "Additionally, ATP-citrate lyase (ACLY) and angiotensin 17 (Ang-17) have been confirmed to modulate LPS-induced inflammation through regulating the metabolism of sepsis-related cells." (PMID 39712019, 2024).
acute myeloid leukemia (6 papers, 2018 to 2024). Acute myeloid leukemia (AML) is a group of neoplasms arising from precursor cells committed to the myeloid cell-line differentiation. "The researches on acute myeloid leukemia (AML) showed that low expression of ACLY is associated with favorable prognosis." (PMID 34823530, 2021). "In addition, low ACLY expression predicts a good prognosis in patients with acute myeloid leukaemia." (PMID 38426936, 2024).
Autoimmunity (6 papers, 2013 to 2023). The occurrence of an immune reaction against the organism's own cells or tissues. "Moreover, ACLY inhibitors with pharmaceutical potentials are apparently of interest for immunotherapy of autoimmunity and unwanted inflammation and certainly require further investigations." (PMID 34491895, 2021).
bladder cancer (6 papers, 2018 to 2024). "In bladder cancer, we screened seven hub genes (ACLY, CNP, NKIRAS2, P3H4, PDIA6, VPS25 and XPO1) associated with survival." (PMID 37601252, 2023). "In addition, ACLY was found with a higher expression level in the tumor cells of bladder cancer than in the normal cells." (PMID 32640634, 2020). "Coordinated upregulation of FASN, ACLY, and pentose phosphate dehydrogenases that provide NADPH for palmitate biosynthesis, suggest that the rate of lipogenesis is also elevated in human bladder cancer." (PMID 29396722, 2018). "In our previous study, we showed that the activities of fatty acid synthase (FASN), ATP citrate lyase (ACLY), and the dehydrogenases of pentose phosphate pathway are significantly higher in human bladder cancer than in adjacent benign tissue." (PMID 29396722, 2018). "In addition, ACLY, NKIRAS2, XPO1 and tumor purity were significantly positively correlated (p < 0.001), which further indicates that ACLY, NKIRAS2 and XPO1 may be potential targets for the treatment of bladder cancer." (PMID 37601252, 2023).
esophageal cancer (6 papers, 2020 to 2024). A primary or metastatic malignant neoplasm involving the esophagus. "In other types of cancer, ACLY upregulation has been shown to promote metastasis and invasion and to inhibit apoptosis in prostate, colon, breast, and esophageal cancer cells." (PMID 36428851, 2022). "Recently, HNRNPA2B1 was shown to function as an oncogenic factor in promoting esophageal cancer progression by the up-regulation of fatty acid synthesis enzymes ACLY and ACC1." (PMID 34395102, 2021). "KRT80 might induce the chemoresistance by lipid droplet assembly and ACC1- and ACLY-mediated lipogenesis in esophageal cancer cells." (PMID 38241178, 2024). "In esophageal cancer, the m6A reader HNRNPA2B1 promotes the expression of ACLY and ACC1, which increases lipid accumulation." (PMID 38560499, 2024). "KRT80 knockdown suppressed anti-apoptosis, anti-pyroptosis, migration, invasion, chemoresistance, and lipogenesis in esophageal cancer cells (p < .05), while ACC1 and ACLY overexpression reversed the inhibitory effects of KRT80 on lipogenesis and chemoresistance." (PMID 38241178, 2024).
non-alcoholic fatty liver disease (6 papers, 2019 to 2025). "Studies have shown that HRD1 interacts with ACLY in non‐alcoholic fatty liver disease, thereby promoting ACLY ubiquitination leading to its degradation." (PMID 38426936, 2024). "Similarly, inhibition of ACLY with bempedoic acid reduces lipid droplet accumulation and fibrosis in mouse models of diet-induced non-alcoholic fatty liver disease." (PMID 40636718, 2025). "METTL3/14 in a non-alcoholic fatty liver disease (NAFLD) model increased the m6A modification and protein level of ATP citrate lyase (ACLY) and stearoyl-CoA desaturase 1 (SCD1), which promoted cholesterol production and lipid droplet deposition." (PMID 36830642, 2023).
Hyperglycemia (5 papers, 2022 to 2026). An increased concentration of glucose in the blood. "In diabetic kidney disease, hyperglycemia upregulates and promotes nuclear translocation of ACLY, fueling histone acetylation and the transcription of pro-fibrotic genes, while also contributing to oxidative stress and lipid peroxidation." (PMID 41958067, 2026). "To test this, we investigated the effect of ACLY inhibition on alanine/glutamine-induced hyperglycemia and hepatic alanine flux." (PMID 41220581, 2025). "However, pretreatment with BMS-303141 markedly attenuated alanine- and glutamine-induced hyperglycemia, suggesting that ACLY activity contributes to hepatic glucose labeling through amino acid–mediated pathways, likely involving ALT transamination." (PMID 41220581, 2025). "Indeed, ATP citrate lyase inhibition during hyperglycaemia partially restored the capacity of lung cDC1 and cDC2 to induce T cell expansion and expression of the proliferation marker Ki-67." (PMID 38093014, 2023). "Pharmacologic ACLY inhibition attenuated alanine- and glutamine-induced hyperglycemia and normalized alanine labeling within 2–4 h, without altering aminotransferase gene expression." (PMID 41220581, 2025). "We found that ATP citrate lyase (ACLY), acetyl-Co-A carboxylase (ACACA) which converts acetyl-CoA into malonyl-CoA, fatty acid synthase (FASN) and acetyl-CoA desaturase (SCD) were increased in normoglycemia in MIC26 KOs but mostly unchanged in hyperglycemia." (PMID 39393820, 2024).
breast tumor (4 papers, 2016 to 2022). "We showed that hyperphosphorylation in ATP citrate lyase (ACL) occurs frequently in human breast tumors and correlates well with HER2+ and/or PIK3CA-mutant (HER2+/PIK3CAmut) status in breast tumor cell lines." (PMID 27015560, 2016).
chronic kidney disease (4 papers, 2024 to 2026). Impairment of the renal function secondary to chronic kidney damage persisting for three or more months. "ACLY also promotes renal fibrosis in chronic kidney disease via pathways such as AKT/ACLY signaling." (PMID 41958067, 2026).
clear cell renal cell carcinoma (4 papers, 2020 to 2026). "In clear cell renal cell carcinoma, ACLY expression is upregulated through HIF-2α/LPCAT1/FBXW7 and VHL/PPARγ axes, promoting lipid synthesis, tumor proliferation, and metastasis." (PMID 41958067, 2026). "The micro peptide ACLY‐BP encoded by LINC000887, which is inhibited by GATA3, maintains ACLY acetylation, preventing ACLY ubiquitination and degradation and stabilising ACLY to produce acetyl‐CoA, resulting in lipid synthesis and promoting cell proliferation in renal clear cell carcinoma." (PMID 39778006, 2025).
endometrial cancer (4 papers, 2022 to 2024). Primary or metastatic malignant neoplasm involving the endometrium (mucous membrane that lines the endometrial cavity). "Many lipid metabolism-related genes, including ACLY, were found to be abnormally expressed in endometrial cancer tissues in Dai’s investigation." (PMID 37664033, 2023). "Additionally, ACLY’s nuclear translocation has been shown to enhance proliferation of endometrial cancer cells by regulating pyrimidine metabolism." (PMID 39399493, 2024).
heart failure (4 papers, 2023 to 2025). Inability of the heart to pump blood at an adequate rate to meet tissue metabolic requirements. "Genetic variants in genes encoding ACLY are associated with the risk of cardiovascular events; however, the role of ACLY in heart failure remains to be explored." (PMID 37233656, 2023). "This has potential translational relevance because prior myocardial transcriptomic analysis of human heart failure with reduced ejection fraction (HFrEF) or heart failure with preserved ejection fraction (HFpEF) found ACLY expression significantly reduced." (PMID 40499285, 2025).
leukemia (4 papers, 2019 to 2023). A malignant (clonal) hematologic disorder, involving hematopoietic stem cells and characterized by the presence of primitive or atypical myeloid or lymphoid cells in the bone marrow and the blood. "At the same time, we provide several critical pathways associated with low ACLY expression, and demonstrate that inhibition of ACLY led to proliferation arrest in THP-1 and MOLM-13 leukemia cell lines." (PMID 31077215, 2019). "The knockdown of ACLY in the two leukemia cell lines resulted in growth arrest." (PMID 31077215, 2019). "We found silencing ACLY expression does reduce the proliferation of leukemia blasts in vitro." (PMID 31077215, 2019). "It was shown that low expression of ATP Citrate Lyase (ACL), the enzyme that initiates lipid synthesis through Acetyl-CoA production, is associated with favorable prognosis in patients with AML, and that discontinuation of cell growth was achieved when ACL was inhibited in leukemia cell models." (PMID 36983080, 2023). "Thus, our results demonstrated that ACLY may promote leukemia growth with prognostic significance and can potentially be used as a novel drug target in the future." (PMID 31077215, 2019). "In parallel, silencing ACLY expression with the inhibitor SB-204990 significantly reduced the proliferation of MOLM-13 and THP-1 leukemia cell lines." (PMID 31077215, 2019). "The implication of ACLY expression levels as an independent prognostic factor and its involvement in multiple pathways suggest that ALCY may be functionally important for maintaining the continuous proliferation of leukemia cells." (PMID 31077215, 2019). "Moreover, ACLY silencing induces proliferation arrest in THP-1 and MOLM-13 leukemia cell lines." (PMID 31077215, 2019). "The relative low expression of ACLY, ACC, and FASN in GC-resistant NALM-6/HDR cells pointed out that targeting FAS might not a good idea for certain patients of relapsed/refractory leukemia." (PMID 34823530, 2021).
lymph node metastasis (4 papers, 2019 to 2024). "The expression of ACLY is associated with lymph node metastasis in GA." (PMID 35785165, 2022).
oesophageal cancer (4 papers, 2023 to 2024). "To further explore the role of ACLY in ESCC, we analysed the expression of ACLY in oesophageal cancer by bioinformatics and molecular biological methods." (PMID 38426936, 2024). "GPR176 might induce chemoresistance by ACC1- and ACLY-mediated lipogenesis and lipid droplet assembly in oesophageal cancer cells." (PMID 37584712, 2023). "In our previous study on oesophageal cancer (ESCA), the m6A reader HNRNPA2B1 upregulated the expression of ATP citrate lyase (ACLY) and acetyl-CoA carboxylase (ACC1), two fatty acid synthetic enzymes, and promoted ESCA progression and metastasis." (PMID 36632454, 2023).
prostate tumor (4 papers, 2016 to 2025). "Key enzymes and transcription factors, such as FASN, ACLY, SREBPs, and FABPs, which are mainly regulated by androgen receptor signaling, orchestrate a lipogenic phenotype that supports prostate tumor growth and survival." (PMID 41009695, 2025). "It has also been shown that targeting ACLY significantly reduces the growth of lung and prostate tumor xenografts." (PMID 35681609, 2022). "Further analysis of prostate tumour lysates revealed that up-regulation of PPARG correlated with increased levels of its downstream metabolic effectors such as Fatty acid synthase (FASN), acetyl-CoA carboxylase (ACC) and ATP citrate lyase (ACLY)." (PMID 33654198, 2021).
brain tumors (3 papers, 2022). "Elevated levels of ACLY have been discovered in patients with brain tumors, so PUFA ω-3 could contribute to a reduction in the risk of developing these tumors." (PMID 35159548, 2022). "We identified increased mRNA levels of ACLY, ASS1 and ODC1 in medulloblastoma primary tumors compared to other pediatric brain tumors, suggesting an increased reliance in medulloblastoma on polyamines, arginine biosynthesis and the TCA cycle/production of acetyl-CoA." (PMID 35267619, 2022). "Consistent with in vitro results, the levels of acetyl‐CoA and ACLY activity were upregulated in FABP7wt compared to control, but not changed in FABP7mut, suggesting that the interaction between FABP7 and its ligands regulates caveolin‐1 expression through histone modification in brain tumors." (PMID 34716958, 2022).
coronary artery disease (3 papers, 2018 to 2022). "Both MR and RCT evidence show ACLY inhibition reduce LDLc levels and proportionately coronary heart disease risk by a similar amount to statins." (PMID 33731105, 2021).
diabetic nephropathy (3 papers, 2025 to 2026). "Our study demonstrated the protective effects of metformin against diabetic nephropathy by the following two key mechanisms: reprogramming macrophage metabolism through SDH- and ACLY-driven pathways and attenuating inflammation-induced senescence." (PMID 41471323, 2025). "In diabetic nephropathy models, VDR activation alleviates lipid peroxidation by modulating ATP citrate lyase (ACLY) and the Nrf2/Keap1 axis." (PMID 41164167, 2025).
fibrosis (3 papers, 2024 to 2026). the formation of excess fibrous connective tissue in an organ or tissue in a reparative or reactive process. "ACLY silencing or ACLY inhibition alleviates diet-induced MASH and CCl4-induced fibrosis in rodents." (PMID 39872142, 2024).